MLANA (melan-A)
Diseases named in the same sentence as MLANA in open-access papers (continued):
Sharing a sentence is not in itself a finding about the gene and the disease.
melanoma (continued). "Moreover, comparative binding studies on Melan-A-specific CD8+ T cell clones derived from a melanoma patient with A2/Melan-A dimers, tetramers, octamers containing linkers of different length and flexibility revealed striking differences depending on the state of CD8+ T cell differentiation." (PMID 23908656, 2013). "On immunohistochemistry, the atypical cells showed diffuse, strong positivity for melanoma markers including SOX10, HMB-45, Melan-A, and S100." (PMID 40236344, 2025). "We defined clusters corresponding to melanoma (PMEL, MLANA), immune infiltrates (TRBC2, TRAC, TMSB4X), melanophages (CD74, LYZ), keratinocytes (KRT14, TRIM29), blood vessels (CAVIN1, PECAM), and fibroblast‐enriched areas in the dermis (DCN, COL1A2, FBLN1)." (PMID 39846232, 2025). "Advanced imaging (MRI) and immunohistochemical analysis revealed the mass to be a superficial spreading melanoma expressing SOX10, PS100, Melan-A, HMB-45, and PRAME." (PMID 39862670, 2025). "The differential diagnosis from melanoma is achieved by excluding melanocytic markers (i.e., S100, HMB-45, and Melan-A)." (PMID 41568379, 2025). "Skin biopsy revealed recurrent melanoma, with SOX10 and Melan-A positivity, and imaging showed features concerning for multifocal disease recurrence in the left popliteal fossa." (PMID 41312331, 2025). "Histological markers used to diagnose melanoma are: S100 protein, HMB45, Melan-A, Tyrosinase, MITF and Vimentin." (PMID 39862670, 2025). "Immunohistological results typically indicate positive malignant melanoma-related markers (HMB-45 and Melan-A) and muscle lineage markers." (PMID 40099082, 2025). "IHC studies showed positivity for vimentin and Melan-A and negativity for CD117 and S100, confirming the diagnosis of melanoma." (PMID 41280416, 2025). "The histological and immunostaining findings were consistent with the preoperative biopsy results; immunohistochemical (IHC) was positive for human melanoma black 45 (HMB-45), S-100, Cluster of Differentiation 57 (CD57), and Melanoma Antigen (Melan A)." (PMID 40320509, 2025). "Both CCS and melanoma share an expression of melanocytic markers, including S100, HMB-45, and Melan-A, as well as similar morphological characteristics, such as large epithelioid cells with clear cytoplasm and prominent nucleoli." (PMID 40004764, 2025). "Tumor cells from both modalities were highly similar, and key melanoma marker genes—including S100A1, MLANA, MCAM, and PRAME—were consistently highly expressed." (PMID 41446065, 2025). "Sarcoma histological markers are sometimes common with melanomas detection (for example, S100 protein, vimentin, exceptionally HMB-45 and Melan-A)." (PMID 39862670, 2025). "Immunostaining was positive for Melan A and partially positive for HMB-45, leading to a diagnosis of malignant melanoma." (PMID 40320509, 2025). "The original tumor cells exhibited diffuse positivity for PRAME and SOX10, while they were focally positive for Melan-A and very focally positive for HMB45, confirming the diagnosis of melanoma." (PMID 40437181, 2025). "Immunohistochemistry can aid in diagnosing melanoma, using markers such as S100 protein, HMB45, and Melan-A." (PMID 39996151, 2025). "Specific immunohistochemical staining revealed a few cells that were positive for human melanoma black 45 (HMB-45) and Melan-A." (PMID 39792728, 2025). "In this retrospective case-control study, we compared 10 cases of SSM with prominent nest, 26 cases of nested melanoma, and 36 dysplastic nevi in terms of their immunohistochemical PRAME and Melan A staining." (PMID 40941765, 2025). "Analysis of key melanoma signature markers revealed that MITF and MLANA were highly expressed in Cluster 1, indicating a differentiated state." (PMID 40386826, 2025). "Here, the expression of PRAME, SOX10, Melan-A, and HMB45 which are routinely used for melanoma diagnosis were evaluated." (PMID 40437181, 2025).
melanoma (continued). "All tumors underwent routine IHC to confirm the LMS diagnosis utilizing smooth muscle markers (SMA, desmin, or H‐caldesmon) and melanoma markers (HMB45, Melan A) to exclude PEComa." (PMID 39691991, 2025). "When considering melanoma in the differential diagnosis of PUC, a panel of melanocytic markers, including S-100, Melan-A, HMB-45, and SOX10, is typically employed." (PMID 40893790, 2025). "Other melanoma-specific markers such as human melanoma black 45 (HMB45), tyrosinase, MART-1/Melan-A, melanocyte-inducing transcription factor (MITF), and sex-determining region Y-box 10 (SOX10), aid in melanoma diagnosis." (PMID 40177537, 2025). "The co-expression of PAX3 with Melan-A, a specific marker for melanocytes, confirms that the PAX3+ cells in the melanoma tissues are of melanocytic origin." (PMID 40216818, 2025). "Histopathology revealed melanoma cells, and immunohistochemistry showed strong positivity for S-100, HMB-45, and Melan-A." (PMID 41204535, 2025). "Definitive IHC of the resection specimen confirmed melanoma, showing S100 negativity but positivity for HMB45, Melan-A, and SOX10." (PMID 41458594, 2025). "For P1, clusters enriched in ER lumen-associated proteins (CIP2A, OSMR, WWTR1), inflammasome-related proteins, and melanoma-specific proteins (CCND1, MITF, MLANA, NOTCH1) were notable." (PMID 40669378, 2025). "Rectal immunohistochemical detection: CK EMA (-) (-), Vimentin (+) S - 100 (+) oven HMB 45 (+) - (+) the SOX Melan - A - 10 (+) about (-) CK56 P40 (-) (-) Ki - 67 (+ 70%), in accordance with melanoma." (PMID 40900782, 2025). "In primary CNS melanoma cells, positive expression of HMB45, S-100, and Melan A is observed, while meningeal epithelial membrane antigen, cytokeratin, neuron-specific enolase, and glial fibrillary acidic protein are expressed negatively." (PMID 41536409, 2025). "Melan-A and PNL-2 immunoreactivity was detected as brown cytoplasmic staining in all samples, confirming the diagnosis of melanoma." (PMID 41295661, 2025). "Classically, the immunohistochemistry reveals strong positivity for melanocytic markers, such as human melanoma black 45 (HMB-45), Melan A, S100 protein, and SOX10 (SRY (Y sex determination region) - Box 10)." (PMID 40978962, 2025). "Emergency surgery was performed to control the bleeding, and subsequent histopathological analysis confirmed a diagnosis of amelanotic malignant melanoma, supported by immunohistochemical positivity for S100, HMB45, Melan-A, and P16." (PMID 40395262, 2025). "Some of the earliest successes of TCR therapy were seen in 2006, where MART-1 (Protein melan-A), a TAA in melanoma, was targeted by TCR-Ts and demonstrated tumor regression." (PMID 39941782, 2025). "Melanoma markers such as SOX10, HMB-45, Melan-A, and S100 help distinguish metastatic melanoma from primary colonic malignancies." (PMID 40236344, 2025). "One possible mechanism involves shared antigens between melanocytes and melanoma cells, such as tyrosinase and related proteins TRP-1 and TRP-2, gp100 and Melan-A." (PMID 39125477, 2024). "Among the samples, 76.5% (52/68) were positive for S-100, 94.1% (64/68) for HMB-45, 83.6% (56/67) for Melan-A, 100% (29/29) for SOX-10, and 76% (19/25) for PRAME (preferentially expressed antigen in melanoma)." (PMID 39728033, 2024). "Immunohistochemical analysis revealed positive reactions for S-100 protein, antihuman melanoma black-45 (HMB-45) antibody, vimentin (VIM), Sox-10, melan-A, vascular endothelial growth factor, and glial fibrillary acidic protein." (PMID 39495986, 2024). "Immunofluorescence staining was performed for the MM_Immune marker, IGKC, and the melanoma marker, Melan-A (MLANA), in formalin-fixed paraffin-embedded tissues of melanoma samples demonstrated an increased MM_Immune cell ratio in the NPD-pre group." (PMID 38505619, 2024).
melanoma (continued). "A panel of immunohistochemical stains, including Inhibin-α and preferentially expressed antigen in melanoma (PRAME), is proposed for use in rare instances of Melan-A-positive GCTs." (PMID 38854338, 2024). "A retrospective analysis of primary melanomas of the oral cavity indicated that 100% of participants were positive for S-100 and HMB-45 markers, while only 57.1% tested positive for Melan-A." (PMID 39006602, 2024). "Adequate conjunctival biopsies were stained with hematoxylin and eosin, Melan-A, SOX10, and PReferentially expressed Antigen in Melanoma." (PMID 37924948, 2024). "Key immunohistochemistry markers for diagnosing malignant melanoma include HMB-45, S-100, melan A, and vimentin." (PMID 39449907, 2024). "As expected, TNF decreased the gene expression of MITF and its target genes MLANA, DCT and TYR, and, conversely, increased the expression of the stemness factor NGFR in 451Lu melanoma cells." (PMID 39136013, 2024). "Tyrosinase, Melan-A/MART-1, gp100, TRP-1, and TRP-2 are the proteins identified by studies on melanoma against which autoreactive CD8+ T lymphocytes are activated." (PMID 38921184, 2024). "Currently, the main markers that are used for the diagnosis and detection of melanoma are S100, HMB-45, Melan A, MITF, SOX 10, microRNA, exosomes, and Melanoma-Inhibiting Activity (MIA)." (PMID 39319051, 2024). "Immunohistochemical staining was positive for smooth muscle actin (SMA), human melanoma black 45 (HMB 45), and Melan A." (PMID 39781125, 2024). "Markers like HMB-45, HMB-50, tyrosinase, melan-A, and MITF also show differences in expression between these two types of melanomas." (PMID 38392052, 2024). "The results of the test were positive for MLANA, S100β, PNL2, TRP1, and TRP2, confirming that this was a malignant melanoma." (PMID 38891124, 2024). "Therefore, the final diagnosis of primary malignant melanoma (amelanotic type) with neuroendocrine differentiation was established based on histological features and the co-expression of melanocytic and neuroendocrine markers such as Melan-A, HMB-45, and synaptophysin." (PMID 39280438, 2024). "The cytoplasmic positivity of Melan-A and HMB45 encountered only in melanoma cells allows for a correct counting of Ki67 only in the tumor proliferation." (PMID 38927524, 2024). "Various melanocytic markers such as S100, HMB45, Melan A, tyrosinase, MITF, and SOX10 can aid in the detection and subtyping of melanoma." (PMID 37958863, 2023). "MITF has been extensively studied in melanoma cells where its transcriptional activity modulates target genes involved in pigmentation, such as TYR, MC1R, DCT, and MLANA." (PMID 37898636, 2023). "The purity of the established cell cultures was confirmed after the first passage via immunofluorescence analysis of the widely used melanoma markers, such as HMB45 or Melan-A, and was also monitored in the subsequent passages." (PMID 37175742, 2023). "Metastatic melanoma is also S100 positive, but will be positive for more specific markers such as HMB45, melan A, tyrosinase and microphthalmia transcription factor." (PMID 38163055, 2023). "Histopathology confirmed the diagnosis of melanoma based on the melanocytic markers, SOX-10 and Melan-A; dedifferentiation was demonstrated within the orbital tumor." (PMID 37559849, 2023). "Conversely, overexpression of wild-type (WT) MITF in non-melanoma 293T cells increased GREB1 Is4, PMEL, and MLANA mRNAs." (PMID 37658191, 2023). "Melanoma is usually identifiable using IHC targeting S100 protein, SOX10, MART-1 (Melan A), MITF1, and HMB45." (PMID 36941503, 2023). "PM shares the immunophenotype of melanomas, including expression of SOX-10, S100, Melan-A, and HMB-45." (PMID 37898793, 2023). "This type of tumor regularly expresses melanocytic markers such as HMB45 and Melan A, but much less rarely expresses S100 or SOX10, which are always positive in melanomas with an epithelioid or spindle-shaped morphology." (PMID 36564790, 2022).
melanoma (continued). "For this stage, there are several markers for melanoma-initiation, such as MAGE proteins, GalNAc-T, NG2, CSPG4, ABCB5, MAGEA3, PAX3, TGFB2, TYR2, Human Melanoma Black-45 (HMB-45), Melan-A, tyrosinase, and S100." (PMID 35565234, 2022). "Hematolymphoid markers (CD45, B cell, and T cell), myogenic markers (myoglobin, desmin, myogenin), melanoma markers (HMB 45, melan A, tyrosinase) and Ewing’s sarcoma markers (CD99/MIC2) are absent in most ONB cases." (PMID 36452830, 2022). "Collagen stiffness induced the expression of melanoma differentiation genes TRPM1, PMEL, TYR and MLANA, as well as well as the proliferation and survival genes CDK2 and BCL2A1." (PMID 36135194, 2022). "We confirmed that CCKAR+ and CCK+ cells were melanoma cells by staining these specimens with antibodies against the common markers of melanoma, HMB-45 and Melan A." (PMID 36262666, 2022). "In a phase I trial, the differentiation antigen Melan-A/MART-1 peptide combined with Class B CpG 7909 and IFA was administered to patients with melanoma." (PMID 35651800, 2022). "While gross specimens that clearly arise from nerves lend credence to a diagnosis of MPNST, negative staining for cytokeratins and melanoma markers like Melan-A, MITF, and HMB45 can be useful in distinguishing MPNST from carcinoma and melanoma." (PMID 35244537, 2022). "All cases in this study were IHC stained for melanoma markers (SOX10, S100, Melan-A, and HMB45) and all were positive for primary cutaneous melanoma, uveal melanoma, and conjunctival melanoma." (PMID 36289768, 2022). "In this context, melanoma cell lines display strong melanocytic features, such as upregulation of melanocytic antigens MART-1 (also known as MLANA) and gp100 (also known as PMEL) and increase in MITF expression." (PMID 36551603, 2022). "Our tentative work from melanoma FFPE samples exhibited comparable and reproducible data for Melan-A." (PMID 36572710, 2022). "The most important tool in confirming the melanoma diagnosis was IHC with melanoma markers SOX10, S100, HMB45, and Melan-A." (PMID 36289768, 2022). "We also examined the transcription of melanin synthesis genes TYR, TYRP1, PMEL, MLANA and DCT by RNAseq analysis in M14 human melanoma cells in which we have disrupted TXNRD1 using Crispr/Cas9 (M14TXNRD1+/− cells)." (PMID 36291795, 2022). "This staining pattern is different from melanoma, which is normally diffusely positive for SOX10 and S100, along with more specific melanoma markers, including Melan-A and HMB45." (PMID 36135073, 2022). "Although both melanoma and nevi stain positive for S100 and SOX10, markers such as Melan-A, HMB45, and Ki-67 can help differentiate them." (PMID 36289768, 2022). "Gene signatures from group 2 corresponded to a proliferative and differentiated phenotype of melanoma (DCT, MLANA, TYR)." (PMID 35053440, 2022). "Immunostaining confirmed the expression of Melan-A, SRY-box transcription factor 10 (Sox10), human melanoma black-45 (HMB-45), and tyrosinase-related protein 1 (TRP1) (green) in all cultured CD90−CD117+ cells." (PMID 35269891, 2022). "Some melanomas stain positive only for one of the markers employed in our laboratory, HMB45 and Melan-A." (PMID 35198980, 2022). "Immunostaining of the tumor biopsy showed positive staining for Melan-A, human melanoma black-45 (HMB45), and S-100 protein (+), indicating malignant melanoma of the esophagogastric junction." (PMID 34882298, 2021). "Another early study showed that a pan-PKC inhibitor, Gö 6983, blocked WNT5A-mediated melanoma dedifferentiation in vitro, with increased expression of PAX3 and melan-A." (PMID 34604096, 2021). "Immunostaining was positive for Melan A, HMB45, S-100 protein, and SRY-box transcription factor 10, and the final diagnosis was malignant melanoma of the esophagogastric junction, with regional lymph node metastases." (PMID 34882298, 2021).
melanoma (continued). "A large number of other melanocytic markers have been subsequently investigated including HMB45, Melan A, tyrosinase, MITF, and SOX10, and are increasingly used in the diagnosis of melanoma." (PMID 34449584, 2021). "Immunostaining was positive for Melan-A, HMB45, S-100 protein and SRY-box transcription factor 10, and the patient was diagnosed with malignant melanoma of the esophagogastric junction with regional lymph node metastases." (PMID 34882298, 2021). "TNFα effects were reversible in both melanocytic (SKMel28, MP46, MEL270, OMM1) and dedifferentiated (HT144, MM200) melanoma cell lines, with the partial to complete restoration of MITF and Melan A expression after TNFα removal." (PMID 34073253, 2021). "We examined TNFα effects on melanoma differentiation by analyzing the accumulation of the key marker proteins MITF, Melan A, AXL and NGFR in the 40 melanoma cell lines." (PMID 34073253, 2021). "When we treated melanoma cells with forskolin, a strong stimulator of the cAMP pathway that leads to MITF activation as visible by MLANA expression, the H2O2-mediated upregulation of EGFR was prevented." (PMID 33916908, 2021). "In daily practice, the IHC-panel usually includes S100 protein and at least one of the three members of the conventional pan-melanoma cocktail: Human melanoma black 45 (HMB45), MART1/melan-A, and tyrosinase." (PMID 33801642, 2021). "Although we did not perform statistical analyses on the three transitory melanoma cell lines, TNFα clearly reduced both MITF and Melan A levels and concurrently increased NGFR and AXL expression in this melanoma subtype." (PMID 34073253, 2021). "To investigate this possibility, we undertook flow cytometry analysis of the B16/F10 melanoma cells used for the tumor formation assays, using antibodies specific for MITF and MLANA." (PMID 33789714, 2021). "Peptide vaccines against melanoma are most often based on gp100, MAGE, Melan A (MART-1), and NY-ESO." (PMID 34696168, 2021). "Markers, including vimentin, S-100 protein, neuron-specific enolase (NSE), Melan A, PNL2, human melanosome-specific antigens -1 (HMSA-1), and HMSA-5 have been assessed for their potential in aiding the diagnosis of canine malignant melanoma." (PMID 34822634, 2021). "Immunostaining of the tumor biopsy showed positive staining for Melan-A, human melanoma black-45 (HMB45), and S-100, indicating malignant melanoma of the esophagogastric junction." (PMID 34882298, 2021). "Both MUG Mel3 NPF and MUG Mel3 NPh highly expressed each of the stained melanoma markers HMB45, Melan-A, Tyrosinase, and MCSP." (PMID 34768746, 2021). "In daily practice, the conventional pan-melanoma cocktail (HMB-45, melan-A, and tyrosinase), along with S100 can be successfully used for the identification of the melanocytic origin of tumor cells." (PMID 33801642, 2021). "The independent prognostic value was proved for the conventional pan-melanoma cocktail (triple positivity for HMB-45, melan-A, and tyrosinase) and, independently for HMB-45 and tyrosinase, but not for melan-A, SOX10, or SOX11." (PMID 33801642, 2021). "Another 14/40 melanoma cell lines (13/31 cutaneous and 1/9 uveal) displayed the neural crest-like dedifferentiated subtype with low MITF and Melan A, and elevated, albeit variable levels, of AXL and/or NGFR." (PMID 34073253, 2021). "In this report, upregulation of Melan-A/MART-1 gp-100 and MAGE-A1 in melanoma cell lines exposed to this cytokine was described." (PMID 34639014, 2021). "mAb used in human medicine for diagnosis of melanomas that cross-react with canine melanomas include human melanosome-specific antigens-1 (HMSA-1), HMSA-5, and Melan A." (PMID 34822634, 2021). "The patient underwent surgical resection of the tumor, and was pathologically diagnosed as neonatal congenital malignant melanoma; immunohistochemistry (IHC): S-100 (+), HMB45 (+), Melan A (+), and Tyrosinase (+)." (PMID 33706747, 2021).